VAV3 (vav guanine nucleotide exchange factor 3)
Description:
Exchange factor for GTP-binding proteins RhoA, RhoG and, to a lesser extent, Rac1. Binds physically to the nucleotide-free states of those GTPases. Plays an important role in angiogenesis. Its recruitment by phosphorylated EPHA2 is critical for EFNA1-induced RAC1 GTPase activation and vascular endothelial cell migration and assembly (By similarity). May be important for integrin-mediated signaling, at least in some cell types. In osteoclasts, along with SYK tyrosine kinase, required for signaling through integrin alpha-v/beta-1 (ITAGV-ITGB1), a crucial event for osteoclast proper cytoskeleton organization and function. This signaling pathway involves RAC1, but not RHO, activation. Necessary for proper wound healing. In the course of wound healing, required for the phagocytotic cup formation preceding macrophage phagocytosis of apoptotic neutrophils. Responsible for integrin beta-2 (ITGB2)-mediated macrophage adhesion and, to a lesser extent, contributes to beta-3 (ITGB3)-mediated adhesion. Does not affect integrin beta-1 (ITGB1)-mediated adhesion (By similarity).
Tractability: Antibody: its Gene Ontology location is reachable by antibodies, with medium confidence. PROTAC: ubiquitination databases record sites on it; its protein half-life has been measured.
Gene: Protein-coding gene on chromosome 1 (107,571,161 to 107,965,180, reverse strand). Ensembl gene ENSG00000134215.
Pathways (Reactome):
Signal Transduction: CDC42 GTPase cycle; G alpha (12/13) signalling events; NRAGE signals death through JNK; RAC1 GTPase cycle; RAC2 GTPase cycle; RHOA GTPase cycle; RHOG GTPase cycle; VEGFA-VEGFR2 Pathway; VEGFR2 mediated vascular permeability
Immune System: DAP12 signaling; FCERI mediated Ca+2 mobilization; FCERI mediated MAPK activation; Regulation of actin dynamics for phagocytic cup formation
Developmental Biology: EPH-ephrin mediated repulsion of cells
Disease: FCGR3A-mediated phagocytosis
Drug ADME: Azathioprine ADME
Hemostasis: GPVI-mediated activation cascade
Gene Ontology:
Molecular function: guanyl-nucleotide exchange factor activity; protein binding; GTPase activator activity; epidermal growth factor receptor binding
Biological process: B cell receptor signaling pathway; DNA damage response; positive regulation of B cell proliferation; response to xenobiotic stimulus; cell migration; Fc-epsilon receptor signaling pathway; Fc-gamma receptor signaling pathway involved in phagocytosis; immune response-regulating cell surface receptor signaling pathway; platelet activation; positive regulation of phosphatidylinositol 3-kinase/protein kinase B signal transduction; regulation of small GTPase mediated signal transduction; small GTPase-mediated signal transduction; intracellular signal transduction
Cellular component: immunological synapse; cytoplasm; cytosol; plasma membrane
Genetic constraint (gnomAD): Loss-of-function variants: 65 observed, 94.85 expected, observed/expected ratio (o/e) 0.69, 90% interval 0.56 to 0.84. The upper end of that interval is the gene's LOEUF score, 0.84, which puts it in group 3 of 6, group 1 being the genes least tolerant of losing a copy. Missense variants: 762 observed, 849.6 expected, observed/expected ratio (o/e) 0.9, 90% interval 0.84 to 0.95. Synonymous variants: 283 observed, 295.37 expected, observed/expected ratio (o/e) 0.96, 90% interval 0.87 to 1.06.
Homologues: Orthologues: chimpanzee VAV3 (98% identical), rabbit VAV3 (97% identical), dog VAV3 (97% identical), mouse Vav3 (95% identical), rat Vav3 (95% identical), macaque VAV3 (93% identical), guinea pig VAV3 (89% identical), tropical clawed frog vav3 (77% identical), zebrafish vav3b (68% identical), zebrafish si:ch73-383g2.1 (22% identical), zebrafish vav3a (13% identical). Paralogues in human: VAV1 (59% identical), VAV2 (55% identical), MCF2L (17% identical), KALRN (17% identical), TRIO (16% identical), ARHGEF7 (16% identical), TIAM2 (15% identical), TIAM1 (15% identical), PLEKHG1 (14% identical), MCF2 (14% identical), PLEKHG4B (14% identical), ARHGEF40 (13% identical), and 10 more.
Diseases named in the same sentence as VAV3 in open-access papers:
VAV3 is named in the same sentence as 102 diseases in open-access papers, as found by Europe PMC text mining. Sharing a sentence is not in itself a finding about the gene and the disease. The quoted sentences say what the papers report.
breast cancer (31 papers, 2007 to 2026). A primary or metastatic malignant neoplasm involving the breast. "By contrast, there are specific functions associated with the maintenance of breast cancer epithelial integrity that can be redundantly performed by Vav2 and Vav3." (PMID 31100928, 2019). "This is probably due to the functional link of this Vav2;Vav3-dependent signature with the tumorigenic and lung-associated metastasis properties of breast cancer cells." (PMID 30087437, 2019). "We have reported here that Vav2 and Vav3 contribute to maintain the epithelial phenotype and associated molecular traits of breast cancer cells." (PMID 30087437, 2019). "(ii) A mirror-image expression of the NR2F1 transcript with those encoding the Vav2, Vav3 and E-cadherin proteins in a large variety of human breast cancer cell lines." (PMID 30087437, 2019). "Vav3 is also present in breast cancer, associating with poorly differentiated lesions." (PMID 32322580, 2020). "VAV3 accelerates cell proliferation of breast cancer, gastric cancer, endometrial cancer, osteosarcoma, and acute lymphoblastic leukemia, and accelerates cell migration and invasion of breast cancer, pancreatic cancer, gastric cancer, and osteosarcoma." (PMID 40028163, 2025). "This study highlights the critical role of two VAV family members, VAV2 and VAV3, in regulating the mevalonate pathway in breast cancer cells through a RAC1‐ and SREBF‐dependent mechanism." (PMID 39119789, 2025). "In studies of prostate and breast cancer, VAV3 acted as an oncogene to activate androgen receptors and estrogen receptors to promote the growth of cancer cells." (PMID 38649819, 2024). "Subsequent to this discovery, VAV3 has been found to be overexpressed in various cancers, such as breast cancer, colorectal cancer, and gastric cancer." (PMID 35392234, 2022). "We have previously identified a number of Vav2;Vav3-dependent distal transcriptional targets in breast cancer cells." (PMID 30087437, 2019). "In the case of breast cancer, we have recently shown that the expression of Vav2 and Vav3 is important for both the primary tumorigenesis and lung metastasis formation." (PMID 30087437, 2019). "VAV3 upregulation (Rho exchange factor) has been described in lung cancer metastasis and breast cancer." (PMID 31027181, 2019). "The in silico analysis of microarray datasets also suggested that the abundance of VAV2 and VAV3 transcripts is associated with low and high levels of CDH1 and NR2F1 transcripts in human breast cancer cell lines, respectively." (PMID 30087437, 2019). "Genome expression profiling experiments further indicate that Vav2 and Vav3 promote both common and family member-specific changes in the transcriptome of breast cancer cells." (PMID 31100928, 2019). "On the basis of such findings, further studies, such as VAV3 gene and protein expression in breast cancer samples from Sardinian cases in relation to the genotype, will help in better understanding the association of the SNP with the disease." (PMID 25956309, 2015). "Vav3 was also shown to be significantly upregulated in breast cancers compared with benign breast diseases." (PMID 26353933, 2015). "Specifically, VAV3 is overexpressed in luminal breast cancer cells, and this drives a transcriptional program for metastatic dissemination to the lungs." (PMID 25248717, 2014). "The results of this study suggest that VAV3 function mediates the response to endocrine therapies in breast cancer and, as a result, the acquisition of resistance." (PMID 24886537, 2014). "VAV3 is basally expressed in all different breast cancer subtypes despite a preferential overexpression in luminal breast cancer, thus suggesting that mechanisms other than promoter methylation regulate its differential expression." (PMID 25248717, 2014). "In this study, we have identified VAV3 as a critical mediator of endocrine therapy resistance in breast cancer downstream of ERα and growth factor receptor signaling." (PMID 24886537, 2014).
breast cancer (continued). "VAV3 mRNA levels tend to be higher in luminal-derived breast cancer cell lines than in basal-like cancer cell lines or normal mammary cells." (PMID 25248717, 2014). "We found that knockdown expression of Vav3 significantly inhibited both estrogen-dependent and -independent growth in these breast cancer cells (Figure 2Eand 2F)." (PMID 18518979, 2008). "Data presented in this report clearly show that Vav3 is overexpressed in human breast cancer and is involved in growth of breast cancer cells and ERα signaling." (PMID 18518979, 2008). "We found that Vav3 was overexpressed in human breast cancer, particularly in the poorly differentiated lesions and in the two most commonly used breast cancer cell lines." (PMID 18518979, 2008). "To determine a potential role of Vav3 in growth of breast cancer cells, we determined the role of Vav3 on estrogen-independent growth in breast cancer cells." (PMID 18518979, 2008). "The current study is to determine a potential role of Vav3 oncogene in human breast cancer and impact on estrogen receptor a (ERα)-mediated signaling axis." (PMID 18518979, 2008). "To determine a potential role of Vav3 in breast cancer, we evaluated Vav3 expression in surgical specimens of human breast cancer by IHC analysis using anti-Vav3 antibody." (PMID 18518979, 2008). "In agreement with its effects on estrogen-independent growth in breast cancer cells, overexpression of Vav3 potentiated EGF-stimulated ERα activation." (PMID 18518979, 2008). "Immunohistochemistry analysis was performed in 43 breast cancer specimens and western blot analysis was used for human breast cancer cell lines to determine the expression level of Vav3 protein." (PMID 18518979, 2008). "The knockdown expression of Vav3 compromised both estrogen-stimulated and -independent growth of breast cancer cells." (PMID 18518979, 2008). "The impact of Vav3 on breast cancer cell growth was determined by siRNA knockdown of Vav3 expression." (PMID 18518979, 2008). "Our data suggest that Vav3 complexes with ERα and its overexpression enhances ERα signaling axis in breast cancer cells." (PMID 18518979, 2008). "We found that Vav3 was overexpressed in 81% of human breast cancer specimens, particularly in poorly differentiated lesions." (PMID 18518979, 2008). "VAV3 is known to be upregulated in various types of cancer, including breast cancer." (PMID 40310419, 2025). "In addition, VAV3 promotes cell migration and invasion in breast cancer, pancreatic cancer, gastric cancer, and osteosarcoma." (PMID 39200159, 2024). "VAV3 gene has been reported methylated in breast cancer and gastric cancer." (PMID 36460706, 2022). "Finally, GEFs like VAV2 showed to be important in squamous carcinomas of the head and neck and VAV3 in glioblastoma and breast cancer." (PMID 32351958, 2020). "The importance of the downregulation of miR-200c is further underscored using GSEAs, as they reveal that a large percentage of the previously characterized miR-200c-regulated transcriptome of endometrial and breast cancer cells becomes upregulated upon depletion of Vav2 and Vav3 in 4T1 cells." (PMID 30087437, 2019). "Here, we report that the Rho GTPase activators Vav2 and Vav3 utilize a new Rac1-dependent and miR-200c-dependent mechanism that maintains the epithelial state by limiting the abundance of the Zeb2 transcriptional repressor in breast cancer cells." (PMID 30087437, 2019). "Thus, reduction of Vav2 and Vav3 expression in mouse mammary tumor cells led to a decline in metastatic growth, similar to the effect of Vav1 depletion in pancreatic cancer cells." (PMID 26353933, 2015). "Moreover, consistent with the role of VAV3 in promoting breast cancer progression, comparatively higher staining was observed at the tumor fronts." (PMID 24886537, 2014).
breast cancer (continued). "In breast tumors, contrarily to Vav2 and Vav3, that play synergistic roles in breast cancer by sustaining tumor growth, neo-angiogenesis and metastasis, the Vav1 transcript seems to be higher in tumors from patients that remained disease free than in patients who developed recurrence." (PMID 24962430, 2014). "In addition, we monitored the expression pattern in those samples of Vav2/Vav3-dependent genes that were common between breast cancer cells and TPA-stimulated keratinocytes." (PMID 23935450, 2013). "Given that steroidal nuclear receptors share many common properties, we hypothesized that Vav3 may regulate ERα activity and is involved in human breast cancer." (PMID 18518979, 2008). "Vav3 stimulates growth of breast cancer cells and activates ERα partially via PI3K-Akt signaling." (PMID 18518979, 2008). "The purpose of this study is to determine the role of Vav3 in breast cancer." (PMID 18518979, 2008). "Taken together, these findings suggest that Vav3 overexpression enhances ERα-mediated signaling axis and may be involved in breast cancer." (PMID 18518979, 2008). "We tested this hypothesis in the present study by examining the expression of Vav3 in human breast cancer specimens and cell lines and investigated a potential role of Vav3 in breast cancer cell growth and ERα signaling." (PMID 18518979, 2008). "We then determined whether knockdown expression of Vav3 inhibits growth of these breast cancer cells using Vav3 siRNA that has been characterized previously." (PMID 18518979, 2008). "We found that Vav3 is overexpressed in human breast cancer specimens and cell lines." (PMID 18518979, 2008). "Likewise, GSEAs reveal high levels of inverse correlation between the Vav2;Vav3-dependent 4T1 transcriptome and the mRNA landscape induced by the ectopic expression of the entire miR-200 cluster in mesenchymal 4TO7 breast cancer cells (which express very low amounts of both miR-200c and E-cadherin)." (PMID 30087437, 2019). "Moreover, VAV3 upregulation correlates with ER and PR expression in breast cancer cells." (PMID 25248717, 2014). "Vav3 overexpression may confer ERα hypersensitivity and play a role in breast cancer." (PMID 18518979, 2008). "Collectively, these findings position VAV3 as a potential key mediator of TNBC progression, bridging signaling, cytoskeletal dynamics, and metabolic adaptation in aggressive breast cancer phenotypes." (PMID 41516402, 2026). "To note, the protein–protein interaction network of PIK3R1, IL1R1, MMP11, GOLM1, and VAV3 altogether connected by EGFR merits further work to understand the mechanism and develop an ideal treatment strategy for invasive small tumor-size breast cancers." (PMID 39190284, 2024). "Such as CMSS1 and ZHX2 in uterine cancer, OSBPL8, FAM214A in breast cancer, TPT1, GPRIN3, and VAV3 in pancreatic cancer." (PMID 37024957, 2023). "During androgen deprivation, Vav3 expression was induced and increased in LNCaP prostate cancer cells activating PI3K-Akt signaling, similar to its action in breast cancer." (PMID 32322580, 2020). "During an earlier work aimed at characterizing the role of Vav2 and Vav3 in breast cancer, we generated a collection of Vav2 (KD2), Vav3 (KD3), and double Vav2;Vav3 (KD2/3) knockdown 4T1 cells." (PMID 30087437, 2019). "The computational pipeline was applied to a panel of 45 breast cancer cell lines, and the protocol identified a list of 58 genes, including COL1A2, TOP2A, TFF1, and VAV3, whose key roles in epigenetic regulation are consistent with known literature." (PMID 20525369, 2010). "We found that Vav3 activates ERα partially via PI3K-Akt signaling and potentiates EGF effect for cell growth and ERα activation in breast cancer cells." (PMID 18518979, 2008). "LG2 markers include 190 genes, among which are many oncogenes, (BCL2 (down, breast cancer poor prognosis marker), RAD51 (up), EGFR (up), RUNX3 (up), BCL9 (down) and VAV3 (down) and tumor suppressor gene NME1 (up)." (PMID 17683614, 2007).
breast cancer (continued). "In the present study, we report that the expression of mevalonate pathway enzymes is mediated by the RHO guanosine nucleotide exchange factors VAV2 and VAV3 in a RAC1‐ and sterol regulatory element‐binding factor (SREBF)‐dependent manner in breast cancer cells." (PMID 39119789, 2025). "Vav3 and HCST play a role in the development of human breast cancer." (PMID 40005880, 2025). "In addition to P-REX1, luminal tumors express high levels of VAV3, a Rho/Rac GEF that was found to drive a lung-specific metastatic transcriptional program in breast cancer cells." (PMID 25248717, 2014). "On the other hand, methylation does not seem to be involved in the upregulation of VAV3, a Rho/Rac-GEF also implicated in breast cancer metastasis, despite the presence of CpG islands in the VAV3 gene promoter." (PMID 25248717, 2014). "Vav3 activated ERα partially via PI3K-Akt signaling and stimulated growth of breast cancer cells." (PMID 18518979, 2008). "Vav3 potentiates EGF activity for cell growth and ERα activation in breast cancer cells." (PMID 18518979, 2008). "Vav3 also potentiated EGF activity for cell growth and ERα activation in breast cancer cells." (PMID 18518979, 2008). "Therefore, methylation plays a major role in controlling P-REX1 expression in breast cancer; however, it does not seem to be a primary mechanism for the control of VAV3 expression." (PMID 25248717, 2014). "Immunoblotting analysis also revealed that Vav3 expression was elevated in MCF-7 and T47D breast cancer cells in comparison with that in nontumoral breast epithelial MCF-10A cells." (PMID 18518979, 2008).